SLFN11 (schlafen family member 11)
Diseases named in the same sentence as SLFN11 in open-access papers (continued):
Sharing a sentence is not in itself a finding about the gene and the disease.
malignant glioma (1 paper, 2022). A grade III or grade IV glioma arising from the central nervous system. "Our investigation began with an analysis of TCGA data, which revealed that SLFN11 expression is inversely correlated with malignant glioma patient survival." (PMID 36382088, 2022).
mucinous carcinoma (1 paper, 2022). "A substantial percentage of SLFN11-negative tumors was observed in mucinous carcinoma (77%), while the other histological types showed no SLFN11 expression in 14–33%." (PMID 35625957, 2022).
ovarian tumors (1 paper, 2021). "Given the correlation of SLFN11 expression in the immune compartment of ovarian tumors with response to cisplatin, we investigated whether this finding could be representative of tumor-immune transactivation." (PMID 34549724, 2021).
pancreatic cancer (1 paper, 2021). "By contrast, combinations with other DDRi (ATMi, olaparib) or other combination strategies (e.g., DDRi (ATRi/WEE1i) + non-DDAi (MEKi used as a representative example)) had the same effect in SLFN11 high and low pancreatic cancer cell lines." (PMID 33339894, 2021). "For example, SLFN11 may be a predictive biomarker to gemcitabine-based treatment regiments: the combination of gemcitabine with either WEE1i or ATRi may be an effective combination strategy in ovarian or pancreatic cancer where most tumours show a low or absent expression of SLFN11." (PMID 33339894, 2021).
paranasal sinus cancer (1 paper, 2022). A primary or metastatic malignant neoplasm involving the paranasal sinuses. "In nasal cavity and paranasal sinus cancers, the SLFN11-positive groups exhibited a significantly superior OS compared to the SLFN11-negative groups (5-year PFS: 86.4% vs. 74.8%, respectively, p = 0.031)." (PMID 36741698, 2022).
ulcerative colitis (1 paper, 2022). An inflammatory bowel disease involving the mucosal surface of the large intestine and rectum. "A study involving an in vitro human ulcerative colitis colon organoid model found that after 60 weeks of inflammatory stimulation the SLFN11 mRNA and protein expression was increased." (PMID 36291149, 2022). "Additionally, the investigators described higher SLFN11 mRNA and protein expression in human endoscopic biopsy samples from patients with ulcerative colitis in comparison to endoscopic biopsies from healthy patients." (PMID 36291149, 2022).
viral infection (1 paper, 2020). "Because the majority of our patients (about 85%) were infected with HBV and 2% were infected with HCV, we speculated that SLFN11 might have additional functions in cytoplasmic in HCC cells under specific condition such as under viral infection." (PMID 32292519, 2020).
cancer (90 papers, 2015 to 2026). A tumor composed of atypical neoplastic, often pleomorphic cells that invade other tissues. "SLFN11 is detected as one of the top predictors of response to SN-38 by the DepMap initiative, with low SLFN11 expression being associated with a decreased sensitivity to SN-38 in 411 pan-cancer cell models." (PMID 39033209, 2024). "Numerous research findings indicate a significant correlation between elevated SLFN11 levels and the susceptibility of cancer cells to these agents that cause DNA damage." (PMID 39558948, 2024). "SLFN11 serves as a predictive biomarker in a wide range of cancer therapies that cause DNA damage, including platinum salts, topoisomerase I/II inhibitors, and lurbinectedin." (PMID 38203275, 2023). "The silencing of SLFN11 by promoter CpG island hypermethylation is linked to a greater resistance to platinum compounds for cancer chemotherapy." (PMID 35216035, 2022). "SLFN11 expression is known to change during the differentiation of B-cell-derived cancers and is associated with chronic intestinal mucosal inflammation and excessive apoptosis in organoid models and patient samples of ulcerative colitis." (PMID 35903760, 2022). "In 2012, two independent research groups discovered by bioinformatic analyses of large cancer cell line panels that the nuclear protein SLFN11 is the causal and dominant genomic determinant of response to DNA-damaging agents." (PMID 35625957, 2022). "Loss of SLFN11 expression in cancer cells involved hypermethylation of its promoter and epigenetic changes in histone acetylation." (PMID 33925464, 2021). "SLFN11-deficient cancer cells heavily rely on the S-G2/M checkpoints following DDA treatment which is sufficient to cope with DNA damage and replication stress to ultimately survive the chemotherapy." (PMID 33339894, 2021). "We summarize key molecular features of DNA replication and discuss how to exploit the RepStress, ATR (ataxia telangiectasia mutated and Rad 3-related) protein kinase inhibitors and SLFN11 for cancer therapy." (PMID 34572827, 2021). "Taken together, our results indicate that SLFN11 is a dual biomarker capturing simultaneously interconnected immunological and cancer cell–intrinsic functional dispositions associated with sensitivity to DDAs." (PMID 34549724, 2021). "In summary, we propose SLFN11 is a dual biomarker capturing simultaneously interconnected immunological and cancer cell–intrinsic functional dispositions associated with sensitivity to DDA treatment." (PMID 34549724, 2021). "The therapeutic benefits of PARP inhibitors are significantly associated with HRD cancers and expression status of SLFN11." (PMID 34572827, 2021). "Schlafen family member 11 (SLFN11) plays an essential role in the DNA damage response, and lack of expression of SLFN11 has been linked to the resistance of cancer cells to DNA‐damaging agents." (PMID 32281704, 2020). "One of the genes that showed consistent down-regulation in CD47-deficient cells was schlafen-11 (SLFN11), which in human cancers is positively correlated with sensitivity of cytotoxic agents including topoisomerase inhibitors." (PMID 31632920, 2019). "Previous studies have identified roles for promoter methylation and epigenetic regulation in the loss of SLFN11 expression in various cancers." (PMID 31632920, 2019). "Background and Aim: Human SLFN11 gene encodes a protein with structural similarity to RNA helicases, which was reported to sensitize cancer cells to DNA-damaging agents." (PMID 31762822, 2019). "Loss of SLFN11 expression in cancer cells involves both hypermethylation of its promoter and epigenetic changes in histone modification." (PMID 31632920, 2019). "There is a proposal to use the expression of SLFN11 as a dual biomarker, capturing simultaneously immunological and cancer cell-intrinsic functional dispositions associated with sensitivity to DNA-damaging treatment in high-grade serous ovarian cancer patients." (PMID 40649874, 2025).
cancer (continued). "Nevertheless, it is hypothesized that SLFN11 may influence DNA replication and repair mechanisms, making cancer cells more susceptible to the effects of DNA-damaging chemotherapy agents." (PMID 38790938, 2024). "These associations indicate immune regulatory roles for SLFN11 that may have clinical translational implications for cancers suffering from immunosuppressive microenvironment." (PMID 38791884, 2024). "Importantly, inhibition of ataxia telangiectasia and rad3-related (ATR) kinase was shown to reverse resistance in SLFN11-deficient cancer cells." (PMID 36382088, 2022). "By screening the NCATS drug library, containing 1978 compounds, we recently reported that TAK-243 (MLN7243), a first-in-class inhibitor of the ubiquitin-activating enzyme UBA1 (also known as UBE1) preferentially suppresses cell proliferation of SLFN11-deficient cancer cells." (PMID 35903760, 2022). "Given that SLFN11 is involved in protein homeostasis through the regulation of cellular protein-ubiquitin adducts, SLFN11 malfunctions may be associated with human diseases beyond cancer." (PMID 35903760, 2022). "Radiation causes DNA damage; hence, SLFN11 expression may correlate with the sensitivity of cancer cells to radiation therapy as well as cisplatin." (PMID 36741698, 2022). "Notably, epigenetic silencing of SLFN11 expression seems to be associated with resistance to specific cancer drugs." (PMID 33450175, 2021). "Our findings add important information on the action of SLFN11 beyond its recently described role; hence, we propose SLFN11 as a dual biomarker capturing simultaneously interconnected immunological and cancer cell–intrinsic functional dispositions associated with sensitivity to DDAs." (PMID 34549724, 2021). "SLFN11 repression occurs frequently in talazoparib-resistant cancer cell lines and was linked with impaired S-phase arrest and G2 progression, which may also be due to fork stabilization." (PMID 32029455, 2020). "Using cells with high or low endogenous SLFN11 expression or cells subjected to siRNA-mediated silencing of SLFN11, researchers showed SLFN11 to be causative in determining cell death and cell cycle arrest in response to DDAs in cancer cells." (PMID 31514451, 2019). "SLFN11 mRNA expression is commonly associated with chemosensitivity in cancer cell lines." (PMID 31682620, 2019). "Thus, the candidate DNA methylation-associated silencing of SLFN11 as a predictor of chemoresistance to platinum agents in cancer became our main focus of interest." (PMID 26625211, 2016). "SLFN11 presents a CpG island located around its transcription start site what makes it a candidate gene for hypermethylation-associated inactivation in human cancer." (PMID 26625211, 2016). "SLFN11 expression is causally associated with activity of DDAs in cancer cells." (PMID 26525741, 2015). "Therefore, SLFN11 may serve as a diagnostic marker, as cancers with low SLFN11 expression are expected to be highly vulnerable to pharmacological inhibition of ATR pathway components when exposed to DDAs." (PMID 38791884, 2024). "SLFN11 belongs to the Schlafen protein family, which has been implicated in the regulation of important biological functions, such as control of cell proliferation and induction of immune responses, regulation of viral replication, and, for cancer, in sensitizing cancer cells to DNA damaging agents." (PMID 26625211, 2016). "Finally, given our in vitro findings that cancer cells with SLFN11 methylation-associated silencing are resistant to cisplatin and carboplatin, we wondered whether the same effect could be observed in clinical samples." (PMID 26625211, 2016). "Prior studies have identified SLFN11 expression as a major determinant of cancer cell sensitivity to DNA-damaging chemotherapeutic agents across several cancers." (PMID 41303540, 2025).
cancer (continued). "One of its core cancer-promoting mechanisms is to activate the PI3K/AKT signaling pathway: SLFN11 knockdown inhibits the phosphorylation of this pathway, and this effect can be reversed by the PI3K activator 740Y-P." (PMID 40766331, 2025). "For different types of cancers, there are some differences in the selection of SLFN11 detection methods (IHC or RNA - seq) and evaluation regions (non - tumor cells, tumor cells, or overall)." (PMID 40766331, 2025). "This methylation was inversely correlated with SLFN11 mRNA levels, which suggests that epigenetic silencing contributes to decreased protein expression in cancer cells." (PMID 41303540, 2025). "Beyond EWS, the broader importance of SLFN11 expression as a sensitivity biomarker in cancer should be investigated, to clarify the threshold of expression required to elicit sensitivity." (PMID 41359388, 2025). "Correlation between high SLFN11 expression and immune activation has been indicated in multiple types of cancer." (PMID 40649874, 2025). "These cancer cell lines of different lineages natively express SLFN11 at levels similar to HAP1 cells." (PMID 41372167, 2025). "Screen specific epigenetic drugs (such as HDAC inhibitors or low - toxicity demethylating agents) targeting SLFN11 promoter methylation or histone modification, and evaluate the differences in their efficacy among different cancer types." (PMID 40766331, 2025). "One of the most striking findings across cancer types is the context-dependent role of SLFN11 in influencing prognosis and therapy response." (PMID 40766331, 2025). "Reactivating SLFN11 via HDAC inhibitors restores cancer cell sensitivity to DNA-damaging agents, while SLFN12 influences immune regulation and chemotherapy response in triple-negative breast cancer." (PMID 41303540, 2025). "In other words, cancer cells that are characterized by high SLFN-11 expression are predicted to be more sensitive to hPARP inhibitors." (PMID 40649247, 2025). "We also review the progress in research on SLFN11 as a biomarker in various cancers, with a focus on SCLC." (PMID 40766331, 2025). "Conversely, reduced acetylation diminishes SLFN11 expression, impairing DNA repair pathways and allowing cancer cells to resist genotoxic stress and continue proliferating." (PMID 41303540, 2025). "In this review, we summarize the structure and function of SLFN11, as well as its progress as a biomarker across various cancer types." (PMID 40766331, 2025). "Our previous immunohistochemical screening of SLFN11 expression in various cancers identified variably positive staining in ~5% of primary CRCs." (PMID 40105034, 2025). "SLFN11 is a putative DNA/RNA helicase that enhances the sensitivity of cancer cells to DNA-damaging agents, such as topoisomerase I/II inhibitors, alkylating agents like carboplatin and cisplatin, and DNA synthesis inhibitors such as gemcitabine." (PMID 40459063, 2025). "With further validation and clinical translation, SLFN11 has the potential to evolve from a predictive biomarker into a central node of personalized cancer therapy." (PMID 40766331, 2025). "Inversely, phosphorylation of the gene inhibited the repressive cell proliferative functions of SLFN11, which normally enabled tumor shrinkage in targeted cancer therapy." (PMID 41303540, 2025). "We assessed the potential contribution of the Schlafen family member 11 (SLFN11) helicase, whose expression is inversely correlated with PARPi sensitivity in other cancers, to the observed resistance." (PMID 40806549, 2025). "SLFN11 expression is emerging as a clinically valuable predictive biomarker for optimization of cancer treatment." (PMID 40105034, 2025). "SLFN11‐positive carcinomas were mostly (21/31, 68%) right‐sided tumors with a female predominance (21/31, 68%) and median age of 67 years." (PMID 40105034, 2025).
cancer (continued). "Studies examining predictive biomarkers for camptothecin derivatives in various cancer cell lines have identified high SLFN11 expression as a biomarker of response to DNA damaging agents, including IIQs." (PMID 39512899, 2024). "The mechanism by which SLFN11 contributes to cancer treatment chemosensitivity involves the irreversible block of stalled replication forks, which eventually leads to cell death." (PMID 39627193, 2024). "SLFN11 plays a crucial role in sensitizing cancer cells to DNA-damaging agents, acts as an antiviral restriction factor and as nuclear immune sensor for ssDNA." (PMID 39627193, 2024). "Previous studies demonstrated the predictive value of SLFN11 in many cancers, including small-cell lung, ovarian, and colorectal cancers." (PMID 37894765, 2023). "Several studies have reported that sensitivity of cancer cells to these DNA-damaging agents is closely correlated with high SLFN11 levels." (PMID 37567892, 2023). "Our data support the notion that the combination of down-regulating SLFN11 via EZH2 inhibitor with chemotherapeutic reagents should be considered in multiple cancer types." (PMID 36775056, 2023). "The estimated effect of SLFN11 on Topotecan is relatively large in lung cancer cell lines compared to other cancer types." (PMID 38081913, 2023). "The epigenetic inactivation of SLFN11-mediated resistance to DNA-targeted agents in different cancers has been bypassed with class I HDAC (Histone DeACetylases) inhibitors." (PMID 38203275, 2023). "In part 6, they assessed not only SLFN11 protein levels in cancer cells but also in different cells of tumor stroma." (PMID 35625957, 2022). "Multiple preclinical models and some clinical studies have demonstrated that high SLFN11 expression levels positively correlate with increased DDA sensitivity in various types of cancers." (PMID 35625957, 2022). "During the last decade, SLFN11 has been extensively studied due to its relevance in cancer research." (PMID 35768579, 2022). "Upon DNA damage, protein phosphatase 1 catalytic subunit γ (PPP1CC) dephosphorylates SLFN11 to increase its activity, thereby sensitizing cancer cells to the topoisomerase I inhibitor, camptothecin." (PMID 35768579, 2022). "Several studies have found that cancer cells with higher SLFN11 expression are more vulnerable to DNA-damaging agents." (PMID 35216035, 2022). "Levels measured by RNA-seq reflected not only SLFN11 positivity in the cancer cell, but also in the surrounding stromal or inflammatory cells." (PMID 35625957, 2022). "Among the SLFN family, SLFN11 has been identified as a critical determinant for the cytotoxicity of anticancer agents targeting DNA replication across multiple cancer types." (PMID 35903760, 2022). "SLFN11 has been identified as a predictive biomarker in cancer, as its expression correlates with a beneficial response to DNA damage inducing anticancer drugs." (PMID 36115853, 2022). "Altogether, data published so far suggest the promising role of SLFN11 as a predictive biomarker in the clinical setting across multiple cancers." (PMID 35625957, 2022). "The ATPase activity of SLFN11 is essential for the killing of cancer cells in response to replicative DNA-damaging agents and chromatin opening, which leads to lethal replication arrest and activation of cellular stress response genes in the FOS-JUN pathways." (PMID 35768579, 2022). "Initially, quantification of SLFN11 expression either in cancer cell lines or patient-derived xenografts (PDX) was performed by transcript analyses using Western blotting." (PMID 35625957, 2022). "SLFN11-low cancer cells then rely on the ATR/CHK1 DNA repair system that enables only reversible cell-cycle arrest in response to replication stress." (PMID 35625957, 2022). "Expression levels of SLFN11 can help to predict the response to a wide range of DNA-damaging anti-cancer agents across multiple cancer types." (PMID 35037067, 2022).